HMOX2 (heme oxygenase 2)
Diseases named in the same sentence as HMOX2 in open-access papers:
HMOX2 is named in the same sentence as 84 diseases in open-access papers, as found by Europe PMC text mining. Sharing a sentence is not in itself a finding about the gene and the disease. The quoted sentences say what the papers report.
diabetes (9 papers, 2011 to 2024). "Heme oxygenase-2 (HO-2) acts as a protective factor against type-2 diabetes and obesity; cadmium has the propensity to alter its catabolism and may increase the risk of diabetes." (PMID 23762083, 2013).
Insulin resistance (7 papers, 2020 to 2025). Increased resistance towards insulin, that is, diminished effectiveness of insulin in reducing blood glucose levels. "Recent studies in humans have linked HMOX2, Nrf2, and IL-1β with insulin resistance and obesity, which are two characteristics exhibited by fasting NES." (PMID 34744798, 2021). "The effect of HMOX2 on obesity and insulin resistance has produced contrasting results in global HMOX2 knockout mice." (PMID 39873298, 2025). "Hmox2-null mice developed insulin resistance, elevated blood pressure, promoted subcutaneous and visceral fat tissue deposition and superoxide production, increased levels of pro-inflammatory cytokines, and decreased serum adiponectin levels." (PMID 38251965, 2024). "In fact, others have shown that Hmox2-/- mice develop the metabolic syndrome at 8 months of age, including obesity, insulin resistance, and hypertension." (PMID 32992485, 2020). "Thus, there appear to be conflicting roles for HMOX2 in the development of obesity and insulin resistance in mice." (PMID 39873298, 2025).
Cognitive impairment (6 papers, 2019 to 2024). Abnormal cognition is characterized by deficits in thinking, reasoning, or remembering. "By co‐expression analysis of the associated omics with the patients’ clinical cognitive decline modules, the role of changed heme oxygenase 2 (HMOX2) and SERPINA3 was highlighted in cognitive impairment." (PMID 36254251, 2022).
Obesity (6 papers, 2013 to 2025). Accumulation of substantial excess body fat. "We assessed body weight of Hmox1-/- and Hmox2-/- mice as well as their WT littermates at 4–5 months of age to determine whether the mice had early evidence of obesity." (PMID 32992485, 2020). "This suggests that the genetic background modifies body weight and adipose phenotype in Hmox2-/- mice or that the small size of the Hmox2-/- initially may lead to later obesity and metabolic dysregulation." (PMID 32992485, 2020).
migraine (4 papers, 2020 to 2023). "TWAS genes with independent effects shared by subtypes of migraine and BP were consistent with findings for overall migraine at ITGB5, while identifying additional associations at HMOX2 for MA and BP, and HVCN1 and MANBA for MO and BP." (PMID 32632093, 2020).
ovarian carcinoma (3 papers, 2017 to 2023). A malignant neoplasm originating from the surface ovarian epithelium. "In contrast, the expression of HIF1A and HMOX2 involved in iron regulation was found to be higher in ovarian cancer tissues." (PMID 38186569, 2023). "Furthermore, using a Human Apoptosis Array Kit consisting of 35 apoptosis-related proteins (R&D) with either miR-141-overexpressing or KLF12 knockdown ovarian cancer cells, 8 out of 35 proteins (HO-2/HMOX2, ph-Rad 17, CIAP-2, survivin, HSP-70, TNFR1/TNFRSF1A, clusterin and XIAP) were upregulated." (PMID 28095864, 2017). "HMOX2, ICMT, MICU1, and TSPAN9 also positively correlated with CD73_1 and CD73_2 densities and short survival and have been shown to be involved in conferring chemoresistance in ovarian cancer." (PMID 33917869, 2021).
Parkinson disease (3 papers, 2015 to 2025). A progressive degenerative disorder of the central nervous system characterized by loss of dopamine producing neurons in the substantia nigra and the presence of Lewy bodies in the substantia nigra and locus coeruleus. "Several reports suggested a role of heme oxygenase genes 1 and 2 (HMOX1 and HMOX2) in modifying the risk to develop Parkinson disease (PD)." (PMID 26091465, 2015).
Sleep apnea (3 papers, 2021 to 2023). An intermittent cessation of airflow at the mouth and nose during sleep is known as sleep apnea. "To better understand the effect of sleep apnea on ECs beyond their activation in the Hmox2-/- model, we performed RNA-sequencing in ECs isolated from Hmox2-/- and Hmox2+/+ mice." (PMID 37844118, 2023). "Consistent with EC activation in sleep apnea, we found that ECs from Hmox2-/- mice showed increased expression of selp and nampt." (PMID 37844118, 2023). "Peng and colleagues have recently described Hmox2-/- mice as a spontaneous model of sleep apnea." (PMID 37844118, 2023).
age-related macular degeneration (2 papers, 2024 to 2025). Age-related loss of vision in the central portion of the retina (macula), secondary to retinal degeneration. "It has been reported that HMOX2 rs1051308 (G554A) SNP is associated with the risk of essential tremors and multiple sclerosis, while HMOX2 rs2270363 (A-42G) SNP is related to the risk of schizophrenia and age-related macular degeneration." (PMID 38251965, 2024).
bladder cancer (2 papers, 2017 to 2020). "HMOX2 (heme oxygenase 2) may be associated with the prognosis of bladder cancer." (PMID 32536039, 2020). "Moreover, CSTF2, POLA1, HMOX2, and EFNB2 may be associated with the prognosis of bladder cancer patient." (PMID 28320388, 2017). "However, HMOX2 and EFNB2 may be the risk factors of bladder cancer." (PMID 28320388, 2017). "HMOX2 (heme oxygenase-2), CSTF2 (cleavage stimulation factor, 3′ pre-RNA, subunit 2, 64 kDa), and POLA1 (polymerase (DNA directed), alpha 1) were the three obviously significant related genes, and a marginal significant correlation was found between EFNB2 (ephrin-B2) and prognosis of bladder cancer." (PMID 28320388, 2017).
breast carcinoma (2 papers, 2021 to 2022). "RELA has shown an increased methylation level that is significant in the progression of breast cancer, HMOX2 has shown an increased hypomethylation in endometriosis, while EZH2 mediates histone modification H3K27m3 and causes several cancers." (PMID 34788504, 2021).
endometriosis (2 papers, 2021 to 2022). The growth of functional endometrial tissue in anatomic sites outside the uterine body. "Endometriosis showed similar or slightly lower levels of Hmox2 (encoding HO-2) and Hx." (PMID 35565370, 2022).
essential tremor (2 papers, 2022 to 2024). A relatively common disorder characterized by a fairly specific pattern of tremors which are most prominent in the upper extremities and neck, inducing titubations of the head. "Heme oxygenase 1rs2071746 and Heme oxygenase 2 rs1051308 polymorphisms can be linked to the cerebellar neurodegenerative model of the pathogenesis of essential tremor." (PMID 36258958, 2022).
heart failure (2 papers, 2020 to 2023). Inability of the heart to pump blood at an adequate rate to meet tissue metabolic requirements. "While enrichment of DEGs in aerobic respiration suggested a change in mitochondrial function as a mechanism for the cardiac changes in Hmox2-/- mice, further studies will be needed to better understand the mechanisms leading to heart failure in these mice." (PMID 37844118, 2023). "In conclusion, we found that Hmox2-/- mice, which spontaneously develop apneas exhibit EC activation and transcriptomic and functional changes consistent with heart failure." (PMID 37844118, 2023). "Using existing gene expression data in the Gene Expression Omnibus (GEO) database, we screened differentially expressed genes (DEGs) of heart failure and identified six key genes (HMOX2, SERPINA3, LCN6, CSDC2, FREM1, and ZMAT1) by random forest classifier." (PMID 33401250, 2020). "Thus, these morphological changes in Hmox2-/- hearts were consistent with dilated cardiomyopathy and heart failure with reduced ejection fraction." (PMID 37844118, 2023).
melanoma (2 papers, 2021 to 2022). A malignant, usually aggressive tumor composed of atypical, neoplastic melanocytes. "Activation of HMOX2 by oncogenic BRAF promotes the increase of melanospheres in melanoma." (PMID 35232428, 2022). "While investigating the association between expression of hub OS genes and SKCM clinical features, we discovered that patients with metastatic melanoma had significantly increased expression of AKAP9, VPS13C, and ACSL4, while HMOX2 demonstrated higher expression in patients with primary melanoma." (PMID 33663112, 2021). "Intriguingly, patients with primary melanoma or higher tumor stage had significantly worse outcomes, which suggested that AKAP9, VPS13C, ACSL4, and HMOX2 might play a vital role in the overall survival of SKCM through mediating cancer growth and metastasis." (PMID 33663112, 2021).
metabolic syndrome (2 papers, 2020 to 2023). A cluster of metabolic risk factors for CARDIOVASCULAR DISEASES and TYPE 2 DIABETES MELLITUS. "This suggests that Hmox2-/- mice develop the metabolic syndrome in an age-dependent manner, consistent with the onset of the metabolic syndrome in individuals who are small for gestational age or intrauterine growth restricted." (PMID 32992485, 2020).
non-small cell lung carcinoma (2 papers, 2017 to 2024). A group of at least three distinct histological types of lung cancer, including non-small cell squamous cell carcinoma, adenocarcinoma, and large cell carcinoma. "Although there are no studies showing the relationship between HMOX2 and cancer yet, HMOX1, a paralog of HMOX2, was known as a poor prognostic predictor and its over-expression may increase the metastatic potential of non-small cell lung cancer." (PMID 28009993, 2017).
polycystic ovary syndrome (2 papers, 2024 to 2025). A disorder that manifests as multiple cysts on the ovaries. "Human polymorphisms in HMOX2 segregate with worse markers of metabolic function in patients with polycystic ovary syndrome (PCOS)." (PMID 39873298, 2025).
Stroke (2 papers, 2017 to 2018). Sudden impairment of blood flow to a part of the brain due to occlusion or rupture of an artery to the brain. "This study aims to examine whether heme oxygenase-2 plays a protective role in mice against stroke." (PMID 30087547, 2018).
Bell's palsy (1 paper, 2025). Partial or complete paralysis of the facial muscles of one side of a person's face. "Our results of the analyses suggest that HMOX2, DEFB128, DDX58 and ITM2A may act as risk factors for Bell’s palsy, but their association with the JAK/STAT signaling pathway is weak." (PMID 40299566, 2025). "In this study, 70 inflammation-related proteins that may be causally associated with Bell’s palsy were identified by MR analysis, and 7 significantly related proteins were screened by external dataset validation, including BLVRB, HMOX2, TNFRSF12A, DEFB128, ITM2A, DDX58 and VEGF-A." (PMID 40299566, 2025).
cardiomyopathy (1 paper, 2023). A disease of the heart muscle or myocardium proper. "In conclusion, our data in Hmox2-/- mice, a spontaneous OSA model, showed expression of genes consistent with EC activation, downregulation of genes involved in cardiac muscle development and contractility, and developed progressive cardiomyopathy." (PMID 37844118, 2023).
Cirrhosis (1 paper, 2023). A chronic disorder of the liver in which liver tissue becomes scarred and is partially replaced by regenerative nodules and fibrotic tissue resulting in loss of liver function. "Using sequencing data related to liver cancer and cirrhosis, we found that HDAC1 and HDAC2 expression was elevated in liver cancer and cirrhosis, and HMOX1 and HMOX2 expression was decreased." (PMID 38127054, 2023).
dilated cardiomyopathy (1 paper, 2023). Cardiomyopathy which is characterized by dilation and contractile dysfunction of the left and right ventricles. "Echocardiographic evaluation showed that Hmox2-/- mice develop progressive dilated cardiomyopathy and conduction abnormalities compared to Hmox2+/+ mice." (PMID 37844118, 2023).
Glucose intolerance (1 paper, 2020). Glucose intolerance (GI) can be defined as dysglycemia that comprises both prediabetes and diabetes. "However, at 4–5 months of age, we saw no changes in insulin sensitivity, glucose intolerance or energy expenditure in Hmox2-/- mice compared to WT littermates." (PMID 32992485, 2020).
ischemic stroke (1 paper, 2023). A stroke disorder caused by obstruction of blood flow to the brain, due to thrombotic (local blood clot formation) or embolic (due to a blood clot or other material traveling from another site) event. "Moreover, Sert prevented the hemorrhagic transformation of ischemic stroke as indicated by the notable decrease in neuronal expression of CD163, activity of Heme oxygenase-2 and matrix metalloproteinase-2 and 9 levels." (PMID 37955765, 2023).
liver cancer (1 paper, 2023). An epithelial or non-epithelial malignant neoplasm that arises from the liver. "Using oleanolic acid-related liver cancer sequencing data, we found that oleanolic acid decreased the expression of HDAC1 and HDAC2 and increased the expression of HMOX1 and HMOX2." (PMID 38127054, 2023).
lung squamous cell carcinoma (1 paper, 2023). "TMEM120B, HMOX2, CALCOCO2, LONP2, ZNF440, CLCC1, and CHMP3 were identified to be optimal prognostic factors for lung squamous cell carcinoma (LUSC)." (PMID 36999050, 2023).
myeloma (1 paper, 2023). "In addition, our microarray data showed that myeloma patient samples exposed to hypoxia had high expression of HMOX1 but not of the isozyme HMOX2." (PMID 36775962, 2023).
pancreatic cancer (1 paper, 2016). "To further resolve if HMOX is involved in anti-proliferative effects of statins on human pancreatic cancer, we silenced HMOX1 and HMOX2 in pancreatic cancer cells with esiRNA and assessed cell proliferation after 48 h of exposure to cerivastatin and hemin." (PMID 27175805, 2016).
peritonitis (1 paper, 2021). Inflammation of the peritoneum (tissue that lines the abdominal wall and covers most of the organs in the abdomen). "Mice genetically deleted for HO-2 (Hmox2−/−) displayed a phenotype of exaggerated inflammatory response in zymosan-induced peritonitis." (PMID 33671004, 2021).
cancer (12 papers, 2016 to 2025). A tumor composed of atypical neoplastic, often pleomorphic cells that invade other tissues. "Results indicated that the four hub genes were all significantly related to metastasis (P < .05); AKAP9, VPS13C, and ACSL4 were positively associated with metastatic ability, while HMOX2 was negatively associated with cancer metastasis." (PMID 33663112, 2021). "Furthermore, we discovered that TiNIR binds to HO2 (heme oxygenase 2), a protein highly expressed in TICs compared to differentiated cancer cells." (PMID 37489464, 2023). "Thus, before utilizing TiNIR, it is important to validate the expression levels of HO2 (heme oxygenase 2) in different stages of cancer cells." (PMID 37489464, 2023). "Therefore, we further investigated connections between AKAP9, VPS13C, ACSL4, and HMOX2 expression and cancer metastasis." (PMID 33663112, 2021). "There are 10 highly significant, direct and physical associators with a confidence score of ≥5.0 namely – RELA, HMOX2, EZH2, p-10Y-ERBB3-1, WDR1, ERRFI1, PRG2, FMR1, DEFA6-(?-100), cytf_human and the majority of the network associators of POTEE are epigenetically activated in many cancers." (PMID 34788504, 2021). "For example, HMOX2 and CLCC1 have been characterized as biomarkers of tumor initiating cells, suppression of which will significantly increase cancer survival." (PMID 35768804, 2022). "Current studies on the roles of HMOX2 and SMPD3 in AML are largely blank, but they play important roles in other cancers, so more preliminary single-gene bioinformatics analyses are needed." (PMID 33117716, 2020).
tumor (11 papers, 2017 to 2025). "Consistent with the results of in vitro experiments, m1A levels and HMOX2 mRNA expression in tumour tissues decreased after CMP1 and CMP9 treatment." (PMID 39763068, 2025). "Our prior study has identified heme oxygenase 2 (HO2) as a promising therapeutic biomarker for the aggressive subsets within tumor." (PMID 38665698, 2024). "In this context, TiNIR has been developed to detect tumor-initiating cells (TICs), with heme oxygenase 2 (HO2) as a promising therapeutic biomarker for tumor-initiating cells." (PMID 37489464, 2023). "Using samples from BLCA patients, a positive correlation was observed between HMOX2 and TRMT61A expression; HMOX2 expression decreased in tumour tissues from mice xenografted with TRMT61A shRNA and increased in tumour tissues from BBN‐driven urinary BLCA mice." (PMID 39763068, 2025). "Enrichment analysis of the global protein expression data across all tumor samples showed that the heme degradation pathway enzymes BLVRA and HMOX2, as well as the mitogenic kinase RPS6KA1, among others, are significantly upregulated in EGFRm samples." (PMID 35360705, 2022).
cardiovascular disease (2 papers, 2023). "Of note, numerous studies showed the impact of the constitutive HMOX2 expression, together with HMOX1, in cardiovascular disease." (PMID 36769209, 2023).
metabolic disorders (1 paper, 2024). "Our findings indicate that HMOX2 G554A and A-42G variations may be linked to endocrine dysfunction of the reproductive system, metabolic disorders of glycolipids, oxidative stress, and body hair growth." (PMID 38251965, 2024). "In conclusion, although we did not observe any association of HMOX2 A-42G and G554A genetic variants with the risk of PCOS in a Chinese population, we found that these polymorphisms are linked to endocrine abnormalities of the reproductive axis and glycolipid metabolic disorders in patients." (PMID 38251965, 2024).
HMOX2 also shares sentences with these, for which no sentence is quoted: Hypertension (6 papers); Cerebral ischemia (5); infection (5); intracerebral hemorrhage (5); ischemia (4); Hyperglycemia (3); lung carcinoma (3); brain injury (2); cerebrovascular diseases (2); endothelial dysfunction (2); hemorrhage (2); injury (2); metastatic cancer (2); multiple sclerosis (2); abortion (1); acute kidney injury (1); allergic rhinitis (1); asthma (1); biliary cirrhosis (1); cardiac arrest (1); chronic mountain sickness (1); chronic obstructive pulmonary disease (1); cleft palate (1); cognitive decline (1); coronary heart disease (1); degenerative diseases (1); disseminated candidiasis (1); hematoma (1); hereditary ataxia (1); hypoxia (1).
A further 20 diseases each share a sentence with HMOX2 in 1 paper.